CXCL8 (C-X-C motif chemokine ligand 8)
Diseases named in the same sentence as CXCL8 in open-access papers (continued):
Sharing a sentence is not in itself a finding about the gene and the disease.
HIV-1 infection (36 papers, 2007 to 2025). The type species of lentivirus and the etiologic agent of acquired immunodeficiency syndrome (AIDS). "Altogether, our results underline the crucial role of PKC delta isoform in activating gene expression of CXCL8, a cytokine largely implicated in the physiopathology of HIV-1 infection." (PMID 28539656, 2017). "We previously reported that HIV-1 infection is linked to upregulation of CXCL8 in brain tissues and human astrocytes." (PMID 24662979, 2014). "Among the cytokines/chemokines produced in the course of HIV-1 infection, CXCL8 has been shown to be important in HIV-1 pathogenesis development." (PMID 28539656, 2017). "In summary, our data suggest a mechanism where elevated CXCL8 levels during HIV-1 infection of the brain promote HIV-1 infection and HIV-1p24 release in human macrophages and microglia." (PMID 24662979, 2014). "The correlation of CXCL8 and HIV-1 infection was demonstrated very early when increased circulating levels of this chemokine were found in HIV-1-infected individuals and also in HIV-1 encephalitis." (PMID 24662979, 2014). "Overall, our study shows that CXCL8 enhances HIV-1 infection in macrophages and microglia through receptors CXCR1 and CXCR2 by downstream activation of NF-κB." (PMID 24662979, 2014). "In this study we investigated the intracellular signaling mechanisms of chemokine CXCL8 in astrocytes in the context of neuroinflammation during HIV-1 infection." (PMID 23029125, 2012). "Our results on HIV-1 infected patients’ CXCL8 levels, combined with previous reports, strongly implicate CXCL8 to be involved in neuroinflammation during variety of neurodegenerative conditions, including HIV-1 infection." (PMID 23029125, 2012). "To confirm the results obtained in MDM and to assess whether CXCL8 promotes HIV-1 infection in human microglia, we infected cultured human microglia with viral isolates HIV-1ADA or HIV-1JRFL." (PMID 24662979, 2014). "We report high levels of CXCL8 in HIV-1 infected individuals, which may be a likely candidate accounting for progressive neurodegeneration associated with chronic HIV-1 infection." (PMID 23029125, 2012). "However, CXCL8 transcripts were significantly downregulated during untreated HIV-1 infection." (PMID 37601355, 2023). "Therefore, the observed increase in HIV-1p24 levels may in part be contributed by endogenous CXCL8 secreted by macrophages during the course of HIV-1 infection." (PMID 24662979, 2014). "Our findings compliment these studies and confirm the role of chemokine CXCL8 and receptors CXCR1/2 in regulating HIV-1 infection in MDM and microglia." (PMID 24662979, 2014). "Since CXCL8 is a key mediator of inflammation during HIV-1 infection and our study highlights its importance in promoting HIV-1 replication, blocking the production or effects of CXCL8 can be a therapeutic strategy." (PMID 24662979, 2014). "HIV-1 infection was monitored by flow cytometry for HIV-1 core proteins and qRT-PCR for unspliced HIV-1 genomic transcripts, while NF-κB activation was measured by qRT-PCR for CXCL8 and BIRC3." (PMID 39269169, 2024). "We demonstrated that CXCL8 was efficient in activating signaling cascades leading to nuclear translocation of NF-κB in macrophages, even in the absence of HIV-1 infection." (PMID 24662979, 2014). "As expected, HIV-1 infection induced expression of IL-1β, IL-6, TNF-α and CXCL8." (PMID 20877724, 2010). "HIV-1 infection upregulated CXCL8 and BIRC3 gene expression, while HIV-1 ∆Vpr did not." (PMID 39269169, 2024).
gingivitis (35 papers, 2014 to 2026). A disorder involving inflammation of the gums; may affect surrounding and supporting structures of the teeth. "IL-6, CXCL8, andCCL2 secretions were significantly higher after exposure to commensal biofilmsthan after exposure to gingivitis or cariogenic biofilms." (PMID 28892653, 2018). "In addition, the proportion of oral microflora, such as oral streptococcus, was also related to the change in CXCL8 levels in gingival crevicular fluid in patients with gingivitis and healthy people." (PMID 37957648, 2023). "A significant dose-dependent increase in the secretion ofcytokines IL-6, CXCL8, CCL2, and CCL5 was found for gingiva equivalents exposedto commensal, gingivitis, and cariogenic microbiome." (PMID 28892653, 2018).
squamous cell carcinoma (34 papers, 2009 to 2025). A carcinoma arising from squamous epithelial cells. "CXCL8 has been shown to be significantly overexpressed in various cancers, including prostate, colorectal, and squamous cell carcinomas of the head and neck." (PMID 40596054, 2025). "CXCL8 has recently been shown to enhance the proliferation and migration of squamous carcinoma cells." (PMID 19819266, 2009). "Furthermore, CXCL8 has recently been shown to enhance the proliferation and migration of squamous carcinoma cells and its elevated secretion in esophageal squamous cell carcinomas has been related to lymph node and distant metastases." (PMID 19819266, 2009). "Recombinant CXCL8 did not stimulate cell growth in either a normal bronchial epithelial or a squamous carcinoma cell line (SKMES-1)." (PMID 21298036, 2011).
vitiligo (34 papers, 2005 to 2025). Generalized well circumscribed patches of leukoderma that are generally distributed over symmetric body locations and is due to autoimmune destruction of melanocytes. "More recent meta-analysis data show that CXCL9, CXCL10, CCL5, CXCL8 (IL-8), CXCL12, and CXCL16 can serve as diagnostic blood biomarkers for vitiligo." (PMID 38673994, 2024). "Highly significant changes in the expression of recruitment and homing-related genes CCL19, CCR7 and CXCL8 were found in growing feathers of vitiligo-expressing Smyth chickens (P < 0.0001)." (PMID 38720888, 2024). "Luteolin has been demonstrated to inhibit the production of IL-8 (CXCL8), a crucial inflammatory chemokine in vitiligo, as well as to stimulate melanin synthesis in cell and zebrafish models." (PMID 37575231, 2023). "In one study, higher concentrations of CXCL8 were present in the blister fluid of vitiligo patients compared to healthy controls with increasing values in patients with progressive disease." (PMID 36911664, 2023). "The increased levels of some chemokines, such as CXCL10 and CXCL8, in the serum and epidermis of vitiligo have been reported in many recent studies." (PMID 35096274, 2022). "Elevated CXCL8 serum levels and increased CXCL8 gene expression in vitiligo patients have been reported recently." (PMID 35096274, 2022). "CXCL12 induces CXCL8 production which is also more pronounced in vitiligo patients." (PMID 36911664, 2023). "CXCL8 levels were higher in active compared to stable vitiligo in 2 studies (P = 0.002)." (PMID 36911664, 2023). "Moreover, compared with stable patients, active vitiligo patients exhibited higher levels of CXCL8 in serum as well as in blister fluid of lesions." (PMID 35096274, 2022). "To check for the possible signs of systemic inflammation, we measured the concentration of inflammation-associated cytokines (TNF-α, IFN-γ, IL-1b, IL-1Ra, IL-2, IL-5, IL-6, CXCL8, CXCL10, G-CSF, and GM-CSF) in the plasma of vitiligo patients." (PMID 30515176, 2018). "Although neutrophil chemoattractant CXCL8 is highly expressed in vitiligo lesions, neutrophils are absent." (PMID 38077333, 2023). "Despite the detectable changes in CXCL8 levels in vitiligo, the well-known function of CXCL8 in mediating the migration of neutrophils rather than T cells is insufficient to elucidate the role of CXCL8 in the pathogenesis of vitiligo, because of the absence of neutrophils in vitiligo lesion skin." (PMID 35096274, 2022).
ZIKV infection (34 papers, 2017 to 2025). "Our results also point to the potential of boosting the IL-1A and CXCL8 pathways as antiviral strategies in ZIKV infection." (PMID 40927453, 2025). "The high concentrations of IL-1b and CXCL8 in the CVL after ZIKV infection suggest that enhanced neutrophil recruitment is a major response to ZIKV replication in the FRT." (PMID 28746373, 2017). "Acutely infected cells produced high levels of pro-inflammatory chemokines, including CCL2, CCL3, CCL4, CCL5 and CXCL8, which could contribute to CNS inflammation during ZIKV infection in vivo by promoting the recruitment of various leukocytes into the CNS." (PMID 32375993, 2020). "Increased serum concentrations of both CXCL (CXCL8 and CXCL10) and CCL chemokines (CCL2, CCL3, CCL4, CCL5, and CCL11) were found in acute ZIKV infection." (PMID 29768624, 2018). "Moreover, ZIKV infection induced an increase in the chemokines CCL3, CXCL9, and CXCL8, while CCL4 and CXCL11 were significantly decreased." (PMID 33430059, 2021). "Moreover, by understanding how mosquito cells respond to ZIKV infection, some key genes such as ITGAL, CXCL8, and THBS1 may be targeted to disrupt the virus’s replication or transmission." (PMID 40927453, 2025). "The samples from pregnant women with ZIKV infection included in this study showed increases in all anti-inflammatory cytokines (IL-10), and some pro-inflammatory cytokines (IL-6, IFN-γ, IFN-α, and IL-17A), chemokines (CXCL10, CCL2, CXCL9, and CXCL8), and receptors (IL-1RA and IL-2R)." (PMID 33430059, 2021). "CXCL3, CXCL8, and PTGS2 were all slightly, but not significantly, induced following ZIKV infection, and the expression of all three inflammatory mediators was significantly decreased in the EGR1−/− infected cells as compared to the WT mock-infected cells." (PMID 35746681, 2022).
glaucoma (33 papers, 2012 to 2026). Increased pressure in the eyeball due to obstruction of the outflow of aqueous humor. "For instance, several inflammatory cytokines and chemokines, i.e., IL-6, TNF, CXCL12, and CXCL8, showed elevated centrality values in various networks, evidencing the detrimental role of neuroinflammation in glaucoma." (PMID 39458974, 2024). "The heat map and decision tree analysis showed that both IL-12 and CXCL8 were signature cytokines for differentiating the glaucoma group from the controls and this was consistent with the univariate analysis." (PMID 22355254, 2012). "Heat map analysis identified the combination of IL-12 and CXCL8 as markers to separate the glaucoma from the cataract group, with an accuracy of 84% for the cataract and 83% for the glaucoma groups." (PMID 22355254, 2012). "Additionally, DLG4 (discs large MAGUK scaffold protein 4) and several proinflammatory chemokines and cytokines already known to have a role in glaucoma, e.g., C-X-C motif chemokine ligand 8 (CXCL8), tumor necrosis factor (TNF), and interleukin-6 (IL-6), were other central nodes in the network." (PMID 39458974, 2024). "CXCL8 and CCL2 are pro-inflammatory cytokines that are elevated in various forms of glaucoma." (PMID 35456925, 2022).
ischemia (33 papers, 2009 to 2025). A hypoperfusion of the BLOOD through an organ or tissue caused by a PATHOLOGIC CONSTRICTION or obstruction of its BLOOD VESSELS, or an absence of BLOOD CIRCULATION. "CXCR1 is a G-protein-coupled receptor activated by the pro-inflammatory chemokine, interleukin-8 (IL-8 or CXCL8), that is up-regulated under acute inflammatory conditions, e.g. after ischemia in the adult rabbit brain." (PMID 20505763, 2010). "The n-6 PUFAs downregulate the expression of chemoattractant production C-X-C motif ligand-1 (CXCL1) and C-C motif ligand-2 (CCL2) on intestinal ischemia/reperfusion injury, as well as n-3 PUFAs inhibit chemokine production such as interleukin-8 (also known as CXCL8)." (PMID 31780872, 2019). "In the setting of MI, chemokines that recruit PMNs to sites of ischemia include macrophage inflammatory protein-2α (MIP-2α, CXCL2, GRO β), leukotriene B4 (LTB4), CINC-1 (CXCL1, GRO α, KC), IL-8 (CXCL8), and complement 5a." (PMID 23731794, 2013). "IL-8, also known as chemokine C-X-C motif ligand 8 (CXCL8), can be induced by injury and ischemia." (PMID 35559255, 2022).
ischemic stroke (33 papers, 2011 to 2025). A stroke disorder caused by obstruction of blood flow to the brain, due to thrombotic (local blood clot formation) or embolic (due to a blood clot or other material traveling from another site) event. "Serum CXCL8 (C-X-C Motif Chemokine Ligand 8, alias of IL-8) level is associated with the infarct volume and functional outcomes in patients with ischemic stroke." (PMID 32194375, 2020). "Similarly, the chemokines CXCL1, CXCL2, and CXCL8 were shown to have neuroprotective effects in a model of β-amyloid toxicity in vitro, however in vivo neutralization of CXCL8 has been shown to mitigate neurological and histological deficits in a model of ischemic stroke." (PMID 26441528, 2015).
esophageal squamous cell carcinoma (32 papers, 2009 to 2025). Esophageal squamous cell carcinoma (ESCC) is a type of esophageal carcinoma (EC) that can affect any part of the esophagus, but is usually located in the upper or middle third. "In patient samples, high expression levels of CXCL8 in esophageal squamous cell carcinoma tissue were significantly associated with lymph node metastasis and poor prognosis." (PMID 39199574, 2024). "Recombinant human CXCL8 induced migration and invasion of esophageal squamous cell carcinoma cell lines by phosphorylation of Akt and Erk1/2." (PMID 39199574, 2024). "Macrophages stimulated with a conditioned medium of esophageal squamous cell carcinoma cell lines showed increased expression of CXCL8." (PMID 39199574, 2024). "Overexpression of CXCL8 was related to tumor progression, metastasis, higher preoperative levels of proinflammatory cytokines, CRP, activation of exogenous coagulation factors, and poor prognosis in esophageal squamous cell carcinoma patients." (PMID 32851080, 2020). "In esophageal squamous cell carcinoma (ESCC), ZC3H13 modulates METTL14/METTL3 nuclear transport and stabilizes CXCL8 mRNA, driving M2 polarization and infiltration, thereby facilitating immune evasion." (PMID 41164187, 2025).
Hepatitis (32 papers, 2009 to 2025). Inflammation of the liver. "CCL20 from iMac and T cells and CXCL8 from iMac were the top two upregulated genes in the hepatitis phase (Right)." (PMID 39135698, 2024). "We identified a population of HBV-specific T cells able to produce CXCL-8 in the setting of liver inflammation; however, this function disappeared as inflammation resolved in acute patients." (PMID 21876747, 2011). "Folate supplementation significantly reduced the expression of pro-inflammatory cytokines TNFα, C-X-C motif chemokine ligand 8 (CXCL8), and LC3B, and improved hepatitis in a dose-dependent manner." (PMID 40740648, 2025). "We also conducted double labeling of CCL20 and CXCL8 with CD68 and CD3, respectively, on liver biopsy samples from HBeAg‐positive hepatitis patients." (PMID 39135698, 2024). "Thus, beyond CXCL-8/IL-8 and VEGF, our in vivo findings indicate a possible involvement of other inflammatory cytokines in surgery-induced liver inflammation that warrant further exploitation." (PMID 31146405, 2019). "Our data demonstrate that HBV-specific T cells produce CXCL-8, but not IL-17, during periods of liver inflammation and that this functional phenotype could be induced in greater than 90% of the detectable virus-specific T cell population in acute/resolved HBV patients by exposure to IL-7 and IL-15." (PMID 21876747, 2011).
meningitis (32 papers, 2006 to 2025). A disorder characterized by acute inflammation of the meninges of the brain and/or spinal cord. "Pro-inflammatory chemokine CXCL8 was increased in viral meningitis, whereas IFN-γ was increased only in the meningitis cause by mumps and enteroviral infection." (PMID 26286516, 2015). "CXCL8 levels were found to be increased in the CSF of EV30 meningitis patients." (PMID 38874395, 2024). "Furthermore, increased concentrations of CXCL1-3 and IL8 (CXCL8) were found in meningitis patients." (PMID 34863201, 2021). "CCL19, CXCL8, CXCL9, and CXCL10 were significantly increased compared to CSF from control patients and compared to levels in serum in patients with encephalitis, meningitis, and Ramsay Hunt syndrome whereas CXCL11 was only increased in CSF in VZV meningitis patients." (PMID 30777092, 2019). "We demonstrate that CNS complications caused by VZV virus are associated with highly elevated CSF levels of the chemokines CCL19, CXCL8, CXCL9, CXCL10, and the matrix metalloproteinase MMP-2 in patients with different CNS manifestations such as encephalitis, meningitis, and Ramsay Hunt syndrome." (PMID 30777092, 2019). "Possession of aliB-like ORF 2 did not affect release of inflammatory cytokine CXCL8 from epithelial cells in culture and the nonencapsulated wild type strain was not able to establish disease or inflammation in an infant rat model of meningitis." (PMID 29580217, 2018).
endometrial cancer (31 papers, 2009 to 2025). Primary or metastatic malignant neoplasm involving the endometrium (mucous membrane that lines the endometrial cavity). "In endometrial cancer, tumour necrosis was associated with a 3.8-fold change in the expression of CXCL8." (PMID 37031328, 2023). "CXCL8 secreted from tumor associated macrophage via HOXB13 promoted endometrial cancer cells invasion." (PMID 36532015, 2022). "CXCL8 secreted by tumor associated macrophages (TAM) inhibits ER + expression in endometrial carcinoma (EC) cells through HOXB13, which may be related to invasion, metastasis, and poor prognosis of cancer." (PMID 34384424, 2021). "TAMs in endometrial cancer promote tumor progression by secreting CXCL8 to reduce the expression of ERα." (PMID 41474538, 2025). "In this case-control study, we aimed to identify the possible associations between selected single nucleotide polymorphisms (SNPs), localized in the CCL2, CCL5, CXCL8, and CXCR2 genes, and the onset and progression of endometrial cancer." (PMID 38001676, 2023). "The reported case-control study of genetic associations was designed to establish the role of selected single nucleotide polymorphisms (SNPs) of the CCL2, CCL5, CXCL8, and CXCR2 genes in the onset and progression of endometrial cancer." (PMID 38001676, 2023). "In turn, for CXCL8, we observed reductions in protein concentration in both cisplatin- and salinomycin-exposed endometrial cancer cultures." (PMID 35625926, 2022). "Significant relationships with endometrial cancer were demonstrated, both for CCL2, CCL5, and CXCL8 chemokines and for the chemokine receptor CXCR2." (PMID 38001676, 2023). "Considering endometrial cancer, a significant relationship was noted between its incidence and pathogenesis on the one hand and CCL2, CCL5, and CXCL8 chemokines, and their selected receptors, including CCR2 (the receptor for CCL2) and CXCR2 (the receptor for CXCL8) on the other." (PMID 38001676, 2023). "Furthermore we have shown that CXCL8 immunolocalised to the same cellular compartment in endometrial adenocarcinomas as the FP receptor and CXCR2 (the receptor for CXCL8) and that CXCL8 expression and release is regulated in endometrial carcinoma explants ex vivo by PGF2α via the FP receptor." (PMID 19819266, 2009).
fibrosis (31 papers, 2009 to 2025). the formation of excess fibrous connective tissue in an organ or tissue in a reparative or reactive process. "In our study, VEGFA and CXCL8, in conjunction with CDKN1A, were the most upregulated genes in fibrosis patients." (PMID 37569323, 2023). "Hence, VEGFA, CXCL8, and CDKN1A, with a mild tendency to be upregulated in fibrosis patients, were markedly induced in the hyperfibrosis ones, with more pronounced signs of conjunctival fibrosis and very early failure of filtering surgery." (PMID 37569323, 2023).